IL15 (interleukin 15)
Diseases named in the same sentence as IL15 in open-access papers (continued):
Sharing a sentence is not in itself a finding about the gene and the disease.
ovarian carcinoma (continued). "These antibody fragments could simultaneously bind with both NK cells and ovarian cancer cells, and the IL-15 portion was applied to specifically mediate IL-15 signaling on NK cells when inducing ADCC effects for triggering robust NK expansion." (PMID 39065636, 2024). "Finally, in a solid tumor model of SKOV3 ovarian cancer treated with a single infusion of anti-TROP2-CAR/IL-15 NK cells (CAR-TROP2/IL-15), CAR-NK cells from Opt-Cs resulted in superior antitumor control and survival compared to those from Sub-Cs." (PMID 38238616, 2024). "IL-15 also acts as a super agonist that enhances NK cell function against ovarian cancer." (PMID 37322531, 2023). "IL-15 enhanced natural killer cell function in ovarian cancer patients." (PMID 34109184, 2021). "Based on our previous findings, we hypothesized that the hyporesponsiveness to IL-2, which we observed in NK cells of certain ascites from women with epithelial ovarian cancer, could be a consequence of impairment of the IL-2 and IL-15 signaling pathways." (PMID 34359872, 2021). "IL-15, which is similar to IL-2, can strongly increase NK cell numbers and may also enhance NK cell function in the ovarian cancer setting." (PMID 30791364, 2019). "Besides, elevated level of IL-5 and IL-15 in rEOC, it is very interesting to find the elevated level of IL-2 in their sera as IL-2 has promising therapeutic potential, a phase II clinical trial has shown its therapeutic benefits in platinum-resistant ovarian cancer patients." (PMID 37322531, 2023). "Although the deletion of IL15 and CXCL10 was consistently observed in independent cohorts of ovarian cancer and lung cancer patients, the direct functional implication of these two genes on TLS formation requires further investigation in future studies." (PMID 37348499, 2023). "Administration of VV expressing a murine IL-15 and IL15 receptor α (IL-15/IL-Rα) complex induced gene expression of NKp46 and NKG2D in murine ovarian cancer tumors suggesting enhanced NK cell infiltration in the tumor." (PMID 38022679, 2023). "We further developed CD16Hi Vδ2 T cells for cancer therapy through CAR and IL-15 engineering and confirmed by in vitro and in vivo characterization that CAR15-Vδ2 T cells display robust antitumor efficacy against ovarian cancer models." (PMID 37938576, 2023). "More recently, Uppendahl and colleagues demonstrated enhanced functionality and cytotoxicity of peritoneal NK cells against ovarian cancer cells after activation with IL12, IL15, and IL18." (PMID 34187852, 2021). "Another example of an anti-cancer CAR γδ T cell is the anti-mesothelin CAR Vδ2 T cell enhanced with increased CD16 expression to augment ADCC, with or without additional increased IL-15 expression, for targeting ovarian cancers." (PMID 40148988, 2025). "The combined immunotherapeutic potential of the IL-15 superagonist and the tumor selective vvDD enhanced survival of mice in IP models of MC38 colorectal and ID8 ovarian cancers, with CD8+ T cells being the key cells mediating vvDD-IL15/Rα antitumor therapeutic efficacy." (PMID 33679747, 2021). "After 21 days of induction with SFTG36 (SCF, FLt-3L, TPO, GM-CSF, IL-3 and IL-6), IS721 (IGF-1, SIS3, IL-7 and IL-21) and IL-15/Hsp70 media, NK cells phenotypes were studied and their cytotoxicity against K562 human erythroleukemia cells and SKOV3 ovarian carcinoma cells was analyzed." (PMID 34098947, 2021). "We have previously shown that NKT cell immunotherapy combined with VSV-GFP enhanced survival in an ID8 ovarian cancer model, and VSV expressing the cytokine IL-15 could combine with NKT cell immunotherapy to reduce growth of Panc02 pancreatic adenocarcinoma tumors." (PMID 38750591, 2024). "Favorable to the use of NK cells as therapeutic target in ovarian cancer treatment, our results showed that ascites, as a tumor environment, did not affect the expression of the CD25, CD122 and CD215 molecules, which comprise the receptors for IL-2 and IL15 cytokines." (PMID 34359872, 2021).
ovarian carcinoma (continued). "Treatment of the ovarian cancer cell line A2780, for 72 hours with 500 nM carboplatin does not lead to overexpression of AIM genes IFI27, IRF7, IL15, or MAGEB2, all of which are increased in AZA-treated cells." (PMID 24583822, 2014). "Similarly, in a xenogeneic mouse model of ovarian cancer, tumor suppression was maintained after 20 days only in mice treated with CIML NK cells, but not with IL-15-stimulated NK cells." (PMID 33742092, 2021).
acute myeloid leukemia (37 papers, 2015 to 2025). Acute myeloid leukemia (AML) is a group of neoplasms arising from precursor cells committed to the myeloid cell-line differentiation. "However, extremely high doses of IL-15 were associated with cytokine release syndrome in the patients with advanced acute myeloid leukemia (AML) and dose-limiting toxicities in the patient malignant melanoma or renal cell cancer." (PMID 33652996, 2021). "IL-15 transpresenting dendritic cells were also able to activate tumor-targeting NK cells, reducing the growth of acute myeloid leukemia cells." (PMID 38980514, 2025). "An IL-15-incorporated NKCE against acute myeloid leukaemia (AML), referred to as CLEC12A TriKE or CD16axIL-15xCLEC12A, has been shown to specifically expand NK cells, but not T cells, leading to the potent killing of AML cells by NK cells." (PMID 37638058, 2023). "Loss of cytotoxicity and defective metabolism are linked to glycogen synthase kinase 3 beta (GSK3β) overexpression in natural killer (NK) cells from patients with acute myeloid leukemia or from healthy donors after expansion ex vivo with IL-15." (PMID 36765663, 2023). "IL-15 can have a mitogenic and anti-apoptotic function in selected subsets of acute myeloid leukemia (AML), confirmed by the expression of the IL-2Rβγ complex by blasts." (PMID 37153603, 2023). "Several clinical trials have shown good outcome and feasibility for the use of IL-15 with NK cells for several cancer types including acute myeloid leukemia, advanced non-small-cell lung cancer and pediatric refractory solid tumor." (PMID 33946954, 2021). "Forty-two patients with refractory acute myeloid leukemia received intravenous (IV) (NCT01385423) or subcutaneous (SC) (NCT02395822) recombinant human IL-15 (rhIL-15) after lymphodepleting chemotherapy and haploidentical NK cell infusions." (PMID 32508818, 2020). "Memory-like NK cells supplemented with IL-12, IL-15 and IL-18 also show enhanced responses against acute myeloid leukemia both in vitro and in vivo, and are currently assessed in a first-in-human clinical trial." (PMID 32762681, 2020). "Currently, CD16 × IL-15 × CD33 TriKE is being evaluated in phase I and II clinical trials in patients with advanced systemic mastocytosis, refractory/relapsed acute myeloid leukemia, or CD33-expressing high-risk myelodysplastic syndromes (NCT03214666)." (PMID 32140153, 2020). "A phase I dose escalation study in patients with acute myeloid leukemia using recombinant IL-15 with adoptively transferred NK cells showed that it was safe and feasible to administer IL-15, and it resulted in persistence and proliferation of NK cells in vivo." (PMID 30805309, 2019). "However, high doses of IL-15 can induce cytokine release syndrome (CRS) in patients with advanced acute myeloid leukemia (AML) and dose-limiting toxicity in patients with malignant melanoma or renal cell carcinoma." (PMID 39682724, 2024). "Moreover γδ T cell expansion starting with peripheral blood mononuclear cells from healthy individuals and acute myeloid leukemia patients is boosted in the presence of IL-15, whereby the antitumor properties of the γδ T cells are strengthened as well." (PMID 27686372, 2016). "Moreover, IL-15-transpresenting DC/NK cell cocultures from both healthy donors and acute myeloid leukemia (AML) patients in remission showed markedly enhanced cytotoxic activity against NK cell sensitive and resistant tumor cells." (PMID 26675759, 2015). "CD16(Nb)/IL-15/CLEC12A(scFv) TriKE was designed for targeting acute myeloid leukemia (AML) via IL-15-activated NK cells." (PMID 36761751, 2023). "CAR-NK cells secreted IL-15 to maintain their anti-relapsed/refractory acute myeloid leukemia (AML) function and exhibited a high anti-AML activity." (PMID 36601109, 2022).
acute myeloid leukemia (continued). "Natural killer (NK) cells from patients with acute myeloid leukemia (AML), or from healthy donors and expanded with IL-15, show defective cytotoxicity and elevated levels of glycogen synthase kinase 3 beta (GSK3β), and drug inhibition of GSK3β was able to improve their cytotoxicity and maturation." (PMID 36765663, 2023). "It should not be underestimated, however, a recent report by Miller JS and colleague describing an in vivo detrimental effect of the systemic administration of engineered IL-15 (IL-15/N-803) in relapsed/refractory acute myeloid leukemia (AML) patients receiving haplo NK cells." (PMID 36230485, 2022). "Notably, NK cells in patients with acute myeloid leukemia (AML) have a higher ability to activate receptors under IL-15 stimulation in vitro and produce higher levels of cytotoxicity against autologous AML cells." (PMID 30813924, 2019). "γδ T cell phenotype of acute myeloid leukemia patients 48-hours after co-culture with IPP, IL-15 dendritic cells (DCs) or both." (PMID 29692776, 2018). "For example, co-expression of IL-15/IL-15Rα and CD80 in syngeneic acute myeloid leukemia (AML) vaccines generated potent, durable anti-leukemic immunity, yielding 50% overall survival in murine models." (PMID 41196843, 2025). "Romee, Fehniger and colleagues demonstrated that stimulation with the cytokines interleukin-12 (IL-12), IL-15, and IL-18 produces so-called cytokine-induced memory-like (CIML) NK cells that exhibited a 56% overall response rate and 44% complete response rate in treatment of acute myeloid leukemia." (PMID 35185932, 2022).
psoriasis (37 papers, 2009 to 2025). An autoimmune condition characterized by red, well-delineated plaques with silvery scales that are usually on the extensor surfaces and scalp. "Because Il15 is within the PSORS9 psoriasis susceptibility locus, this work suggested a potential alternative splicing mechanism by which Il15 contributes to the pathogenesis of psoriasis." (PMID 29515135, 2018). "Polymorphisms in IL15 (rs2857261, rs10519613, and rs1057972) have been associated with psoriasis in a Chinese population." (PMID 24069534, 2013). "IL-15 is also considered a susceptibility gene to the development of psoriasis." (PMID 38405187, 2024). "The present study suggests that the subnetworks involving the IL-23/IL-17 axis and IL-15 cytokine could cause psoriasis via bistable regimes, we explore if this behavior can be exploited in order to find a new treatment option." (PMID 33500449, 2021). "However, in a Caucasian population, no clear association was found between rs1057972 and rs10519613 in IL15 gene and psoriasis." (PMID 24069534, 2013). "For example, shedding of IL-15Ra by endothelial cells has been observed in models of psoriasis as a mechanism to limit the pro-inflammatory effects of IL-15 and thereby dampen inflammation and autoimmunity." (PMID 41209004, 2025). "The roles of cytokines such as TNFα, IL-15, IL-17, and IL-23 in psoriasis have been studied through mathematical/computational models as well as experiments." (PMID 38883205, 2024). "There was a significant increase in IL-17F and IL-17A production in co-cultures of psoriasis skin-homing CLA+ T cells with epidermal cells when stimulated with IL-15 and IL-23This response was reduced around 50 to 80% by blocking HLA class I and II molecules." (PMID 38405187, 2024). "The pro-inflammatory mediators associated with psoriasis are IL1B, IL2, IL6, IL12, IL15, IL17, IL18, and IL20." (PMID 37569685, 2023). "Anti-IL-22 (median: 262.8 vs.190.5, p = 0.0418) antibody was decreased whereas anti-IL-15 (median: 25.5 vs. 30.5, p = 0.0069) was increased in psoriasis patients compared to that in healthy controls." (PMID 36118416, 2022). "We herein showed that of 13 ACAAs examined in this study, only anti-IL-22 and anti-IL-15 in psoriasis differed from those in controls." (PMID 36118416, 2022). "Of 13 anticytokine antibodies, anti-IL-22 was moderately lower (median: 262.8 vs.190.5, p = 0.0418), and anti-IL-15 was slightly higher (median: 25.5 vs. 30.5, p = 0.0069) in psoriasis than controls." (PMID 36118416, 2022). "Further, while investigating the treatment of psoriasis via ‘anti-IL-15’ treatment only one type of signal was assumed to have perturbed the system." (PMID 33500449, 2021). "On the other hand, exogenous IL-15 upregulates Th-17 responses of T cells in psoriasis, possibly by saturating the IL-15Rα containing trimeric receptor complexes and engaging IL-15βγc dimeric receptors." (PMID 34956227, 2021). "Nevertheless, the interactions between cell types relevant for psoriasis that we identified do involve IL-15 and our research indicates that IL-15 links all 3 cell types considered." (PMID 33500449, 2021). "Nevertheless, the modulation of inflammation induced by the IL-15 / sIL-15Rα complex is of major interest in inflammatory diseases such as psoriasis, transplantation or in oncology where the role of IL-15 is well established." (PMID 31996218, 2020). "Blocking IL-15 biological activity reportedly reduced the severity of psoriasis in a xenograft model of human psoriasis." (PMID 32929360, 2020). "We and others have shown that pathogenic TRM cells poised to IL‐17 production persist in close vicinity to LCs with elevated expression of IL23 or IL15 and surrounded by keratinocytes in the epidermis of resolved psoriasis." (PMID 32757303, 2020). "In the skin network, we identify KDs such as ICAM1, IL15, STAT1, TNFAIP3, and GRB2 to be the network hubs connecting numerous genes in the psoriasis-associated supersets." (PMID 30642337, 2019).
psoriasis (continued). "We genotyped seven single-nucleotide polymorphisms (SNPs) in candidate genes of six ILs: IL4, IL10, IL12B, IL13, IL15, and IL23R, which have been shown in the literature to be associated with psoriasis in other ethnic groups." (PMID 24971308, 2014). "Other cytokines and chemokines associated with psoriasis include IL19, IL20, IL15, and MCP1 (monocyte chemoattractant protein)." (PMID 24069534, 2013). "Indeed, anti-IL-15 blockade in psoriasis and vitiligo has been investigated as a promising therapeutic concept in those diseases." (PMID 35755042, 2022). "The presence of IL-15 and IL-23 is increased in lesional skin from psoriasis patients." (PMID 34778294, 2021). "Indeed, evidence linking IL-15 to psoriasis pathogenesis is less abundant than the other cytokines considered above (though see, for example)." (PMID 33500449, 2021). "In addition, we explore the role of IL-15 in the pathogenesis of psoriasis and its potential as a future drug target for a novel treatment option." (PMID 33500449, 2021). "Indeed, we demonstrated before that endogenous soluble IL-15Rα derived from epidermal stroma, protects against dendritic cell/IL-15-mediated, T cell-driven skin inflammation in vivo, and is relevant to human psoriasis." (PMID 31996218, 2020). "In light of investigations in psoriasis and atopic dermatitis, the role of dendritic cells in HS needs to be clarified, as dendritic cell influx has been reported in histological studies, and they may contribute to the high IL-10 and IL-15 levels reported." (PMID 30828428, 2018). "Additionally, tofacitinib's inhibition of IL-15 may play an important role in treating psoriasis as IL-15 is highly expressed with enhanced binding activity in psoriatic lesions and associated with increased resistance to keratinocyte apoptosis." (PMID 24883332, 2014). "In lesional skin from AD and psoriasis patients, scRNAseq revealed increased frequencies of LAMP3+BIRC3+ immunoregulatory DCs, representing a major source of IL15, and CD14+ DC3 cells, expressing the cytokines IL1β and IL23A." (PMID 40534591, 2025). "Clinically, there is a strong correlation among IL-15 levels, IFNg, and cytotoxic capacity of IEL in CD and CD49a+ tissue-resident cells in psoriasis and vitiligo." (PMID 38405398, 2024). "Together, these findings showed that the major profile of ACAAs is at a normal range except anti-IL-22 and anti-IL-15 antibodies, and the titers of single ACAA hardly correlated with psoriasis severity." (PMID 36118416, 2022). "In psoriasis and vitiligo, Trm cells expressing CD49a as a subpopulation of CD8+ Trm cells specifically localize in the basal layers of epidermis and, upon stimulation by IL-15, preferentially produce IFN-γ and display a high cytotoxic capacity." (PMID 35755042, 2022). "Our group has shown that IL-15 and IL-23 act synergistically on cocultures of CLA+ memory T cells and autologous epidermal cells to produce significantly increased levels of IL-17F and IL-17A in psoriasis when compared to CLA− T cells cocultures." (PMID 34778294, 2021). "However, to date there is no psoriasis treatment directly targeting IL-15." (PMID 33500449, 2021). "In particular, serum levels of IL-17A were strongly correlated with IL-1α, IL-15, IFN-γ, IL-18, TNF-α, IL-12B, IL-17F, and IL-22 in psoriasis but not in healthy controls." (PMID 36118416, 2022). "Administration of recombinant IL-15 or CD8+, but not CD4+, TCM cells resulted in complete recurrence of psoriasis in mice previously treated with DHA." (PMID 32929360, 2020).